MYL5 (myosin light chain 5)
Synonyms: MYLC2
Tractability: No criterion of Open Targets' tractability assessment is met for any kind of drug.
Gene: Protein-coding gene on chromosome 4 (673,521 to 682,033, forward strand). Ensembl gene ENSG00000215375.
Subcellular location (Human Protein Atlas): Nucleoli; Nucleoplasm
Pathways (Reactome):
Muscle contraction: Smooth Muscle Contraction
Gene Ontology:
Molecular function: calcium ion binding; structural constituent of muscle
Biological process: regulation of muscle contraction
Cellular component: cytoplasm; cytosol; muscle myosin complex
Genetic constraint (gnomAD): Loss-of-function variants: 28 observed, 20.78 expected, observed/expected ratio (o/e) 1.35, 90% interval 1 to 1.8. The synonymous counts are far from expectation, so gnomAD's model fits this gene poorly and the ratio says little. Missense variants: 274 observed, 217.38 expected, observed/expected ratio (o/e) 1.26, 90% interval 1.14 to 1.39. Synonymous variants: 118 observed, 83.7 expected, observed/expected ratio (o/e) 1.41, 90% interval 1.21 to 1.64.
Homologues: Orthologues: chimpanzee MYL5 (99% identical), macaque MYL5 (98% identical), dog MYL5 (94% identical), pig MYL5 (91% identical), Caenorhabditis elegans mlc-1 (47% identical), Caenorhabditis elegans mlc-2 (47% identical). Paralogues in human: MYL10 (64% identical), MYL2 (63% identical), MYL7 (63% identical), MYL11 (57% identical), MYL12A (54% identical), MYL12B (54% identical), MYL9 (54% identical).
Diseases named in the same sentence as MYL5 in open-access papers:
MYL5 is named in the same sentence as 37 diseases in open-access papers, as found by Europe PMC text mining. Sharing a sentence is not in itself a finding about the gene and the disease. The quoted sentences say what the papers report.
breast carcinoma (5 papers, 2002 to 2025). "In previous results, we found that MYL5 expression was linked with great breast cancer patient prognosis in Kaplan–Meier plotter and PrognoScan datasets." (PMID 36846347, 2023). "The correlations of MYL5 expression with immune cell infiltration and associational gene markers in breast cancer were analyzed by using the TIMER, TIMER2.0, and TISIDB databases." (PMID 36846347, 2023). "MYL5 can serve as a prognostic signature in breast cancer and is associated with immune infiltration." (PMID 36846347, 2023). "Our previous data manifested that the low-expression level of MYL5 was associated with poor prognosis, and further suggested that MYL5 could serve as a good prognostic biomarker to diagnose and treat breast cancer." (PMID 36846347, 2023). "A previous study reported that MYL5 expression is reduced in multiple cancers, including breast cancer, colorectal cancer, esophageal cancer, gastric cancer, head and neck cancer, and leukemia, compared to corresponding normal tissues." (PMID 41358199, 2025). "So, in this part, we first investigated the correlation of MYL5 expression with clinicopathological factors in breast cancer by analyzing the data from the TCGA dataset." (PMID 36846347, 2023). "This study first offers a relatively comprehensive understanding of the oncogenic roles of MYL5 for breast cancer." (PMID 36846347, 2023). "In brief, we concluded that there is a possible prognostic molecular marker for good survival correlated with immune cell infiltration in breast cancer, called MYL5 expression." (PMID 36846347, 2023). "We found that there was a low expression of MYL5 in breast cancer than in corresponding normal tissue by analyzing the data from Oncomine and TCGA datasets." (PMID 36846347, 2023). "In this study, we aimed to elucidate the effects of MYL5 on clinical prognosis and immune cell infiltration, and further explore the potential mechanism in breast cancer patients." (PMID 36846347, 2023). "We also found that the grade of breast cancer markedly affected the role of MYL5 expression on the RFS." (PMID 36846347, 2023). "The results showed that in Kaplan–Meier plotter and PrognoScan databases, the OS, DMFS, RFS, and PPS of breast cancer patients were significantly prolonged in the MYL5 high-expression group, compared with the MYL5 low-expression group." (PMID 36846347, 2023). "To further investigate the biological function of MYL5 in breast cancer, we used the data from the LinkedOmics dataset to explore the coexpression pattern of MYL5 in TCGA-BRCA." (PMID 36846347, 2023). "To further investigate the effect of MYL5 on survival prognosis in breast cancer, we continued to employ the Kaplan–Meier plotter to analyze the effect of different clinicopathological factors on the expression of the MYL5 gene and clinical prognosis." (PMID 36846347, 2023). "In the present study, in order to elucidate the potential value of MYL5 on breast cancer, we investigated the effects of MYL5 expression on survival prognosis, mainly including OS, RFS, DMFS, PFS, FP, and PPS." (PMID 36846347, 2023). "The data of this part demonstrated the stratification analysis about the value of MYL5 expression on survival prognosis, providing evidence for the value of MYL5 to apply diagnosis and therapy on different clinical types of breast cancer." (PMID 36846347, 2023). "This study firstly offers a relatively comprehensive understanding of the oncogenic roles of MYL5 for breast cancer." (PMID 36846347, 2023). "In this study, we first explored the expression pattern and prognostic value of MYL5 in breast cancer across multiple databases, including Oncomine, TCGA, GTEx, GEPIA2, PrognoScan, and Kaplan–Meier Plotter." (PMID 36846347, 2023). "In BRCA patients who were not divided into different molecular subtypes, we found that MYL5 expression and B cell infiltrate collectively affected the prognosis for breast cancer patients." (PMID 36846347, 2023).
breast carcinoma (continued). "In a recent article, MYL5 was demonstrated as a novel biomarker for breast cancer." (PMID 39768172, 2024). "However, to date, there have been few clinical studies to indicate the clinical value and functional role of MYL5 in tumors, especially breast cancer." (PMID 36846347, 2023). "Furthermore, research showed the prognosis of the MYL5 high-expression group was better than the low-expression group in breast cancer patients." (PMID 36846347, 2023). "Followingly, we further investigated the correlation between MYL5 expression and immune-infiltrating cells in the tumor microenvironment, and results showed that MYL5 expression significantly correlated with immune-infiltrating cells and their gene markers in breast cancer patients." (PMID 36846347, 2023). "All data from the Kaplan–Meier plotter dataset of this part demonstrated that MYL5 could be a potential and poor prognostic factor for lung cancer and gastric cancer patients, but a better prognostic biomarker for breast cancer and ovarian cancer patients." (PMID 36846347, 2023). "Therefore, in view of the complexity of tumor occurrence and progression in BRCA (breast invasive carcinoma), it is of great importance for us to clarify the correlation between MYL5 and clinical prognosis, as well as the potential molecular mechanism of great significance in breast cancer." (PMID 36846347, 2023). "In this study, we attempted to explore the effect of MYL5 expression on the prognosis of patients with pan-cancer through bioinformatics analysis using public data sets, and further explore the potential molecular mechanism of MYL5 on the clinical prognosis of breast cancer." (PMID 36846347, 2023). "We divided breast cancer patients into different intrinsic subtypes, including basal (triple-negative), luminal A, luminal B, and HER2+, and explore the role of MYL5 on prognosis in each subtype." (PMID 36846347, 2023). "In many cases, MYL5 expression can prolong the overall survival and relapse-free survival in breast cancer patients with negative lymph node metastasis." (PMID 39768172, 2024). "Myosin light chain plays a vital regulatory function in a large-scale cellular physiological procedure, however, the role of myosin light chain 5 (MYL5) in breast cancer has not been reported." (PMID 36846347, 2023). "The results showed that MYL5 expression could prolong the OS in basal and HER2+ breast cancer patients, and increase the RFS among basal, luminal A, and HER2+ breast cancer patients." (PMID 36846347, 2023). "To verify the conclusion about the association between the expression of MYL5 and immune cell markers, we employed the GEPIA2 tool to analyze the relationship of MYL5 with B cell, M1/M2 macrophage, TAM, monocyte, and T cell exhaustion in breast cancer and normal tissue, severally." (PMID 36846347, 2023). "We first present VNB data that PSE, but not MYL5, is highly overexpressed in breast cancer tissue." (PMID 11953821, 2002). "In the present study, MYL5 expression negatively correlated with the markers of T cells exhaustion, such as PDCD1 (PD-1), CD274 (PD-L1), and CTLA4 (cytotoxic T-lymphocyte antigen 4), which indicated that MYL5 could play a positive role in prolonging survival prognosis for breast cancer patients." (PMID 36846347, 2023). "For lymph node-negative patients, MYL5 expression significantly lengthened the OS and RFS in breast cancer, and for lymph node-positive patients, MYL5 expression only prolonged the RFS." (PMID 36846347, 2023).
gastric cancer (3 papers, 2019 to 2025). A primary or metastatic malignant neoplasm involving the stomach. "As for gastric cancer patients, the OS and PPS in the MYL5 high-expression group were shorter than the MYL5 low-expression group." (PMID 36846347, 2023).
cervical cancer (2 papers, 2019 to 2024). A primary or metastatic malignant neoplasm involving the cervix. "Myl5 mutants can promote metastasis in vivo, which is determined by the overexpression of MYL5 in cervical cancer cells." (PMID 39768172, 2024). "MYL5 can induce gene expression in cervical cancer by binding to the AGCTCC promoter by the HIF-1 start site, upregulating HIF-1 in CC, and increasing cells’ invasive abilities." (PMID 39768172, 2024).
colorectal cancer (2 papers, 2023 to 2025). A primary or metastatic malignant neoplasm that affects the colon or rectum. "In addition, we also found the prognostic difference between the MYL5 high-expression group and the low-expression group among colorectal cancer, soft tissue cancer, acute myelocytic leukemia (AML), and multiple myeloma (MM)." (PMID 36846347, 2023).
lung carcinoma (2 papers, 2019 to 2023). "Similarly, as for lung cancer, the result of OS in the PrognoScan dataset supported the conclusion that the OS of lung cancer patients in the MYL5 high-expression expression group was shorter than the MYL5 low-expression group, indicating that MYL5 could be a poor prognostic factor for lung cancer." (PMID 36846347, 2023). "However, we found that in lung cancer, the OS, FP, and PPS in MYL5 high-expression group were markedly shorter than the MYL5 low-expression group." (PMID 36846347, 2023).
breast tumor (1 paper, 2023). "However, we just used public databases of Oncomine, Kaplan–Meier plotter, GEO, PrognoScan, TCGA, TISIDB, and LinkedOmics datasets to demonstrate the effects of MYL5 on prognosis and immune infiltration in breast tumors." (PMID 36846347, 2023).
endometrial cancer (1 paper, 2025). Primary or metastatic malignant neoplasm involving the endometrium (mucous membrane that lines the endometrial cavity). "MYL5 showed enrichment in pathways related to amino sugar and nucleotide sugar metabolism, butanoate metabolism, cysteine and methionine metabolism, endometrial cancer, metabolism of xenobiotics by cytochrome P450, and retinol metabolism." (PMID 41358199, 2025).
ovarian carcinoma (1 paper, 2023). A malignant neoplasm originating from the surface ovarian epithelium. "The OS, progression-free survival (PFS), and PPS in the MYL5 high-expression group for ovarian cancer patients were obviously longer than in the MYL5 low-expression group." (PMID 36846347, 2023).
type 2 diabetes (1 paper, 2019). "Among the other potentially damaging variants, MYL5 (myosin light chain 5) p.F88S, is in a gene that is one of 10 shown to be regulated by the master trans regulator KLF14, itself associated with levels of HDL‐C and type 2 diabetes." (PMID 31617323, 2019).
cancer (3 papers, 2019 to 2024). A tumor composed of atypical neoplastic, often pleomorphic cells that invade other tissues. "After conducting a prognosis analysis, we first further investigated the relationship of MYL5 expression with cancer-associated fibroblasts (CAF)." (PMID 36846347, 2023). "Furthermore, MYL5 expression is markedly related to the tumor-infiltrating immune cells (TIICs), including cancer-associated fibroblast, B cell, CD8+ T cell, CD4+ T cell, macrophage, neutrophil, and dendritic cell, and related to immune molecules as well as the associated gene markers of TIICs." (PMID 36846347, 2023). "The correlation of MYL5 expression with CAF infiltrate in pan-cancer was exhibited by the heatmap through employing the TIMER2.0 tool, with the EPIC, MCPCOUNTER, XCELL, and TIDE algorithms, respectively." (PMID 36846347, 2023). "To verify the effect of MYL5 on prognosis in pan-cancer, we further explored the prognosis difference between the MYL5 high-expression group and MYL5 low-expression group by Kaplan–Meier plotter and PrognoScan databases." (PMID 36846347, 2023). "The data of this part indicated that MYL5 expression existed a significant difference between pan-cancer and normal tissue, which deserved further investigation." (PMID 36846347, 2023). "The relationship between MYL5 expression and chemokines in pan-cancer was presented by heatmap, and especially, the top 6 scatter plots of the absolute p values showed the negative correlation of the two in BRCA." (PMID 36846347, 2023). "All data manifested that the MYL5 gene could be a potential and novel prognosis factor and it could be of benefit to clinical diagnosis and therapy for different cancers." (PMID 36846347, 2023). "Therefore, the expression difference of MYL5 between cancer tissues and normal tissues was worth further investigation, in order to reveal the value of MYL5 in clinical diagnosis and therapy of tumor patients." (PMID 36846347, 2023). "Therefore, all data of this part demonstrated that MYL5 might be a potential and novel biomarker for specific cancer patients' clinical diagnosis and therapy." (PMID 36846347, 2023). "To further verify the conclusion among the previous data about the effect of the MYL5 gene on prognosis, we used the data from the PrognoScan dataset to study whether MYL5 expression had contributed to a better prognosis for special types of cancers." (PMID 36846347, 2023). "In some cases, overexpression of MLC genes has led to a significant increase in the invasive abilities of cancer cells, as revealed by Matrigel invasion assays of the RLC MYL5 in comparison with control conditions." (PMID 39768172, 2024).
tumor (3 papers, 2019 to 2024). "As Myl5 expression is correlative to prolonged mitotic activity, Myl5 can contribute to tumor formation purely from prolonged mitotic checkpoint activation." (PMID 39768172, 2024). "The low-expression level of MYL5 leads to the worsening of clinical features (primary tumor scope, lymphatic metastasis, and pathological stage of tumor and prognosis)." (PMID 36846347, 2023). "Therefore, it was confirmed that MYL5 participated widely in modulating various immune molecules in BRCA to affect immune infiltration in the tumor microenvironment." (PMID 36846347, 2023).
infection (2 papers, 2013 to 2019). The state of being infected such as from the introduction of a foreign agent such as serum, vaccine, antigenic substance or organism. "We verified the PPARs pathway-mediated generation of ANGPTL4 in BMECs in response to meningitic E. coli challenge and demonstrated for the first time that ANGPTL4-triggered ARHGAP5/RhoA/MYL5 signaling cascade contributed to the BBB disruption by the infection." (PMID 31766605, 2019). "Based on the sequencing data, we additionally investigated the expression alteration of MYL5 in hBMECs at different time points and observed that the MYL5 was significantly increased in hBMECs along with the infection." (PMID 31766605, 2019). "We demonstrated preliminarily that meningitic E. coli induced the expression of ANGPTL4 through the activation of PPARβ/δ signaling pathway, and ANGPTL4 contributed to the infection-mediated BBB disruption via the ARHGAP5/RhoA/MYL5 signaling cascade, affecting the actin cytoskeleton." (PMID 31766605, 2019).
MYL5 also shares sentences with these, for which no sentence is quoted: esophageal cancer (2 papers); head and neck cancer (2); leukemia (2); meningitis (2); acute myeloid leukemia (1); age-related macular degeneration (1); bacterial meningitis (1); breast invasive carcinoma (1); diffuse large B-cell lymphoma (1); dilated cardiomyopathy (1); dyslipidemia (1); E. coli infection (1); esophageal squamous cell carcinoma (1); kidney cancer (1); lymphoid neoplasm (1); metastatic disease (1); multiple myeloma (1); ovarian serous cystadenocarcinoma (1); sarcoma (1); skin cutaneous melanoma (1); testicular germ cell tumor (1); thymoma (1); triple-negative breast carcinoma (1); urothelial carcinoma (1); uterine carcinosarcoma (1).